TNF (tumor necrosis factor)
Diseases named in the same sentence as TNF in open-access papers (continued):
Sharing a sentence is not in itself a finding about the gene and the disease.
cancer (continued). "It is well known that angiogenesis plays an essential role in the progression of cancer; IMiDs also have an anti-angiogenetic effect, reducing tumor necrosis factor-α (TNF-α), vascular endothelial growth factor (VEGF), fibroblast growth factor-β (FGF-β) and interleukin-6 (IL-6)." (PMID 32899586, 2020). "Furthermore, the activation of autocrine and paracrine signals from members of the tumor necrosis factor (TNF) family has a major impact on invasion and metastasis of cancer cells." (PMID 32708030, 2020). "Similarly, another study found that tumor cell debris, after cancer therapy, promotes survival and growth of living cancer cells in multiple tumors through the secretion of pro-inflammatory cytokines such as TNF-α, IL-6, IL-8, CCL4, and CCL5 by macrophages." (PMID 32326073, 2020). "Macrophages derived from GGN-ADC also secreted more proinflammatory cytokines, such as IL-1 and TNF-α, which could recruit CTLs to attack cancer cells (all P < 0.001)." (PMID 33083004, 2020). "In situations in which a functional caspase-8 is deficient, SMs were reported to trigger the production of necrosome, consisting of RIP1, receptor-interacting protein kinase 3 (RIP3), and mixed lineage kinase domain-like (MLKL), thereby promoting cancer cells to undergo TNFα-stimulated necroptosis." (PMID 32325691, 2020). "In addition, there is a possibility that the inhibition of SMPD3 blocks the cytotoxicity of tumor necrosis factor (TNF) in cancer cells." (PMID 32756339, 2020). "A literature search revealed that, among the transcription factors of this cluster, NF-κB and c-Jun were reported to be associated with TNF transcription; but there are no reports about them in cancer cells in response to MTAs." (PMID 31645676, 2020). "Of these, TNF-α is of particular interest as it was identified as a key cytokine for the cytotoxic activity of neutrophils toward breast cancer cells and increased neutrophil transmigration and nitric oxide release that promotes cancer cell killing." (PMID 33105656, 2020). "It was reported that TNF-α increased CDDP sensitivity of cancer cells." (PMID 32784919, 2020). "Considering that miR-381-3p overexpression in both Panc-1 and MKN45 cells enhanced cell resistance to TNF-induced apoptosis, we hypothesized that there is a correlation between the miR-381-3p level and the sensitivity of cancer cells to TNF-induced apoptosis." (PMID 32411707, 2020). "After metastasis, pro‐inflammatory cytokines, including Il1α, Il1β, Il6, Il18, and TNF‐α, were significantly induced in lung metastases, indicating that inflammatory cytokines may play a positive role in cancer metastasis." (PMID 34766117, 2020). "Moreover, BV6 alone or combined with TNFα can exhibit the same anti-cancer effect in pancreatic cancer cells." (PMID 33665167, 2020). "Cancer cells are able to secrete proinflammatory factors (TNFα, IFNγ, IL6, etc.)that enhance the recruitment of immune cells to the inflammation site, including polymorphonuclear neutrophils and eosinophils, monocytes, lymphocytes, natural killer cells (NK), and mature dendritic cells." (PMID 32752264, 2020). "In addition, TNF-α (Tumor necrosis factor), which plays a fundamental role in many disease mechanisms, including cancer, has been shown to activate mTORC1 by phosphorylating the TSC1 complex (IKKβ)." (PMID 32120776, 2020). "Notably, multifunctional CD4+ and CD8+ T cells capable of producing multiple Th1 cytokines (IFN-γ, TNF-α, IL-2) and expressing the degranulation marker (CD107a) play a critical role in cancer protection." (PMID 33105813, 2020). "Tumor necrosis factor (TNF)-related apoptosis-inducing ligand (TRAIL) receptor agonists are an exciting possibility for cancer treatment due to their ability to induce apoptosis in cancer cells while having little effect on normal cells." (PMID 32138282, 2020).
cancer (continued). "Several of the gene sets are associated with oncogenesis, progression, and metastasis of cancer, such as mitotic spindle, hypoxia, Kras signaling up, PI3K-AKT-mTOR signaling, IL6-JAK-STATS3 signaling, mTORC1 signaling, TNF- α signaling via NF- κB, inflammatory response, and Myc targets v1." (PMID 33194434, 2020). "Moreover, TNFα increased the cancer stem cell-like population and stemness phenotype in HPV16-immortalized cells." (PMID 31911577, 2020). "IL-6 and TNF-α increase due to cancer and it is thought that this increase induces neutrophils." (PMID 31122885, 2020). "Thus, it indicated when combined with the natural proteasome inhibitors, celastrol, the anti-cancer activities of TNF-α can enhance." (PMID 33364939, 2020). "We concluded that TNFα activates NF-κB activity in cancer cells, which in turn upregulates the pro-apoptotic target gene CAPS9 at the mRNA level and protein level by direct transcriptional regulation, and indirectly decreases the expression of CASP9 repressor miR1276." (PMID 32225068, 2020). "TNF-α has been reported to play crucial roles in cancer progression and metastasis 26,18." (PMID 32194791, 2020). "Oxidation of cIAP2 was recently shown to regulate TNF-induced apoptosis in cancer cells." (PMID 32290499, 2020). "Tumor necrosis factor-α (TNFα) is closely related to the occurrence of cancer." (PMID 33184404, 2020). "Additionally, SM’s presence during IL-2 priming increases NK cell cytotoxic capacity via activation of the TNF-α–NF-kB axis, prompting to use SM as a novel strategy acting through cancer cell sensitization and NK cell functional enhancement." (PMID 33322371, 2020). "Standard therapy may present some detrimental aspects such as tissue damage, hypoxia and cancer cell apoptosis through the release of proinflammatory cytokines such as TNF-alpha, granulocyte-colony stimulating factor (G-CSF), CXCL12, CCL2-4 and ICAM1." (PMID 32708431, 2020). "The proto-oncogene JUN is associated with the cis-regulatory lncRNA RP4-794H19.1 and is very commonly found in cancers; JUN has been linked to the TNF signaling pathway, and may be a vital gene in NPC." (PMID 32863767, 2020). "In conclusion, we demonstrate that GE5 and GE50 can be used to reduce the levels of the TNF-α and IL-6 cytokines in cancer cachexia mice, and ginsenoside Rb1 can have the same effect; this may potentially be helpful in treating cancer cachexia." (PMID 32020864, 2020). "Thus, further studies are required to determine the downstream signaling from TNFα that synergizes with SM-164 or other IAP antagonists to induce cancer cell apoptosis in order to design a novel effective combined therapeutic approach." (PMID 32332865, 2020). "However, in many cancer cells, immediately after treatment with TNF-α, NF-κB is activated to prevent cell death, grow better, become more invasive, and show better metastasis." (PMID 33233701, 2020). "Previously, we found that GK upregulates the expression of TNF-α and IL-17 in lamina propria and Kupffer cells, which was accompanied by the enhanced MAP kinase level and expansion of cancer stem cells, subsequently leading to inflammation-associated carcinogenesis." (PMID 31941439, 2020). "Cancer cells are then recruited to the metastatic site via TNFα, CXCL2, TGFβ, and S100A8/9." (PMID 32121014, 2020). "To investigate the molecular mechanism(s) underpinning the atrophying activity of muscular RAGE in cancer condition, we used two well‐characterized in vitro models of muscle atrophy consisting of myotube cultures exposed to TNFα alone or in combination with IFNγ." (PMID 32159297, 2020). "Of the potentially nephrotoxic cytokines secreted by cancer cells, an animal model showed that the overproduction of Tumor Necrosis Factor (TNF) could lead to pathological progression in nude mice." (PMID 33260558, 2020).
cancer (continued). "With the cotreatment with LPS, which could boost the expression of cytokines in these cancer cells, berberine significantly reduced the increased expression of TNF-α and IL-6." (PMID 32258115, 2020). "The level of TNF-α was elevated in cancers compared with normal tissues or healthy controls." (PMID 33680949, 2020). "TNF has been used as an anti-cancer drugs in various cancer cells." (PMID 33109189, 2020). "There are controversies regarding the role of TNF-α in cancer." (PMID 32283655, 2020). "However, this strategy should consider proteolysis of APP as well as various substrates, including TNFα and epidermal growth factor receptor ligands involved in inflammation and cancer." (PMID 32028607, 2020). "Similarly, miR-125b was down-regulated in MM patients by cancer-secreted growth factors such as tumor necrosis factor (TNF) and insulin growth factor (IGF)-1." (PMID 33066062, 2020). "Adiponectin could negatively regulate cancer cell growth via regulating inflammatory signaling molecules, including Erk1/2, Akt, tumor necrosis factor (TNF)-α, IL-1β, NF-κB, IL-6, IL-8 and CCL2." (PMID 32787888, 2020). "In recent years, the causal relationship between activation of some inflammatory transcriptional factors such as nuclear factor-kappaB (NF-κB) and production of pro-inflammatory cytokines such as tumor necrosis factor-alpha (TNF-α) with cancers pathogenesis has been a major focus." (PMID 32215331, 2020). "Therefore, the up-expression of CAPS9 contributes to apoptosis of cancer cells, at least in the process of apoptosis induced by TNFα&DOX." (PMID 32225068, 2020). "Thus, previous work has demonstrated that the co-culture of macrophages together with cancer cells induces increased cell migration, which is promoted via the macrophage-mediated release of TNFα (tumor necrosis factor alpha)." (PMID 32751163, 2020). "Our results suggest that IL-17A, IL-17F, and TNF-α measured in the saliva may be a potential biomarker for cancer of the oral cavity and oropharynx." (PMID 32855976, 2020). "In COPD, several TNF blocking agents have reached phase-II clinical trials, but these have been complicated by initial concerns related to increased incidence of cancer compared to the placebo control treatment arms, which were later contested in a long-term follow-up analysis." (PMID 33329046, 2020). "In this scenario, TNFα induces survival and even cancer cell proliferation." (PMID 32391269, 2020). "We also identified associated pathways, such as those of cancer, PI3K-Akt signaling, MAPK signaling, FoxO signaling, focal adhesion, HIF-1 signaling, Ras signaling, TNF signaling, estrogen signaling, toll-like receptor signaling, and VEGF signaling pathway, among others." (PMID 32210799, 2020). "Moreover, hLf-treated mice showed an increase of serum INF-γ, IL-2, and TNF-α, along with a down-regulation of serum IL-4 and cancer tissue VEGF." (PMID 32183434, 2020). "Hence, cytokines like IFNγ and TNFα can play dual roles in cancer progression and the internal complexity of combined receptor signaling strongly affects antitumor responses." (PMID 32733461, 2020). "In particular, MEIS1, FLT3, TNF, PBK, and IGF2BP, all associated with cancer, were down-regulated." (PMID 32698374, 2020). "Similarly, TNF-driven necroptosis in cancer cells can propagate RIPK3-dependent immunosuppression by ablating the release of pro-inflammatory factors, despite proficiently releasing various DAMPs." (PMID 32752206, 2020). "The anti-apoptotic role of MT in some cancers is well known, so we hypothesized that this action could be related to the possible inactivation of a cytokine involved in apoptosis, like TNF-α." (PMID 31936364, 2020). "Indeed, cancer cells’ senescent phenotype can arise in response to TNFα/TNF receptor 1 (TNFR1) through the activation of the p16INK4A/Rb pathway." (PMID 32370259, 2020).
cancer (continued). "Likewise, induction of IDO1 by inflammatory cytokines, including IFNγ and tumor necrosis factor α (TNF-α), has been linked to poor prognosis in CMM as well as various different cancer types." (PMID 32117720, 2020). "Second, TNFα has been recognized as a mediator of ICB resistance in several cancer types." (PMID 32391269, 2020). "A result of the study showed that EPE could increase apoptosis activity through cancer cells which is characterized by increasing TNF-α expression." (PMID 33369455, 2020). "The G-308A polymorphism in TNF-α gene was reported in relation to TNF-α protein production and development of inflammation as well as it was suggested to play an important role in the development and progression of cancer." (PMID 30900134, 2020). "The pretreatment of low dose of TNFα prior to administration of chemotherapeutic agents such as Cisplatin, Paclitaxel, and Gemcitabine improved the efficacy of the agents in the experimental cancer model." (PMID 32219066, 2020). "In addition to the TNF protein,the TNF gene has been employedfor cancer gene therapy and has been reported to promote antitumorresponses both in animal models and in patients." (PMID 32023055, 2020). "Cytokines are small proteins that are essential in shaping protective antitumor immune responses, however, the utility of cytokines in the clinic for cancer immunotherapy is limited, with only TNFα, IFNα, and recombinant IL-2 approved for a small number of cancer indications." (PMID 32457754, 2020). "Furthermore, elevated TNF-α production by many cancer cells will positively feedback in an autocrine fashion to further augment the activation of the NF-κB signaling pathway to promote cancer cell proliferation, migration and invasion." (PMID 32317702, 2020). "Cytokines and other compounds such as DCA, IL-1β, tumor necrosis factor α (TNF-α) and lipopolysaccharide (LPS) may promote expression of COX-2 mRNA and protein in human colorectal fibroblasts, profoundly in cancer-associated fibroblasts (CAF) 25-27." (PMID 32410839, 2020). "However, the potential therapeutic, or even deleterious, effects of targeting TNF in other inflammatory conditions, such as cardiovascular disease and cancer remains equivocal." (PMID 32805626, 2020). "Inflammatory factors such as TNF-α could stimulate accumulation of reactive oxygen species and then inducing DNA damage and genomic instability and might lead to initiation of cancer." (PMID 32134471, 2020). "Moreover, TAM-derived chemokines/cytokines (e.g. TGF-β, IL-6, IL-10, and TNF-α) is shown to enhance stemness of cancer cells by promoting EMT." (PMID 32264958, 2020). "Importantly, TNF-α stimulated cancer cell-MSC or cancer cell-fibroblast co-cultures stimulated endothelial cell migration and sprouting in vitro and increased tumor growth in vivo." (PMID 33414786, 2020). "Subsequently, inflammation can, for example, activate the NF-κB (nuclear factor kappa B) transcription factor and stimulate the production of TNF-α, two critical factors that, when upregulated, may participate in cancer development." (PMID 33383887, 2020). "Another strategy that is now active in solid cancers among which upper GI tumors regards early detection of cancer recurrence by monitoring changes in a panel of circulating inflammatory cytokines (IL-1, 6, 8, 10, 12 and TNF-α) before and after chemo-radiation (NCT00502502)." (PMID 32751137, 2020). "In addition to factors like TNF-α, migrating cancer cells in vasculature can interact with E-selectin on endothelial cell surface and soluble E-selectin shed in shear environments." (PMID 33585411, 2020). "Therefore, chemokines are recognized as key trafficking molecules produced by cancer cells in response to TNF-α stimulation, and able of driving LSPs recruitment." (PMID 31665136, 2019). "Indeed, we found a remarkable induction of RHBDL2 expression by TNFα in both endothelial and cancer cells." (PMID 31783481, 2019).
cancer (continued). "TNF-α mRNA positive cancer cells were only occasionally seen in the central areas of the tumors." (PMID 30999696, 2019). "However, recent studies have found that TNF-α is also an endogenous tumor-promoting factor that can promote the proliferation, invasion and metastasis of cancer cells." (PMID 31440472, 2019). "Considering that steroids likely impair anti-cancer immune responses, anti-TNF may constitute a good alternative strategy to prevent a subset of irAEs triggered by ICB." (PMID 31727152, 2019). "Our observations of TNFα sensitivity of BRCA2-defective cancer cells suggest that BRCA2 mutant tumors may be selectively sensitive to TNFα." (PMID 30626869, 2019). "TNFα is known for its direct effects on cancer cells and for shaping the immune response." (PMID 30872676, 2019). "In this study, we investigated whether PRFR could sensitize TNF-α-induced cell death in lung A549 cancer cells and then act as a potent inhibitor of TNF-α-induced A549 cell metastasis." (PMID 31540489, 2019). "A hallmark of TNFα is its ability to promote pro-inflammatory responses, and therefore deregulation of TNFR-mediated signaling is associated with many inflammatory diseases and cancer." (PMID 31557902, 2019). "Because cytokine secretion by CAR-T cells targeting cancer cells indicates the activation and specific cytotoxicity of T cells, we analyzed the levels of the classic cytokines, TNF-α, IL-10, INF-γ, and IL-2, to assess the cytokine profile when CAR-T cells were incubated with U-251MG cells." (PMID 31288857, 2019). "TNFα, in analogy to NF-κB signaling, has also been described to play a role in cancer." (PMID 30626869, 2019). "Downregulation of these antiapoptotic proteins could enhance TNF-α-induced cancer cell death via autophagy and apoptosis." (PMID 31540489, 2019). "Future studies may disclose whether miR-21 and TNF-α are cooperating, competing or completely independent during cancer progression." (PMID 30999696, 2019). "However, they also secrete anti-cancer mediators such as tumor necrosis factor alpha (TNF-α) and granulocyte-macrophage colony-stimulating factor (GM-CSF)." (PMID 30833944, 2019). "Indeed, similar to TNF-α, TNF-β stimulates an inflammatory cascade in cancer cells and investigations on ovarian tumors have shown that TNF-β is over-expressed in cancer cells and associated fibroblasts." (PMID 30917533, 2019). "Cancer inflammatory environment may be established by several factors, including pro-inflammatory cytokines such as TNF-α, IL-1β, and IL-6." (PMID 31252615, 2019). "Accordingly, inhibition of Zeb1, LIFR: STAT3 signaling as well as blocking the actions of inflammatory cytokines such as tumor necrosis factor α (TNFα) and IL-1β cytokines could confer dormancy and thus eliminate cancer outgrowth." (PMID 31430951, 2019). "Based on its cancer cell-specific expression and ability to modulate TNFα/ERK axis which can alter both cancer growth and metastatic potential, we hypothesized that MADD could also be a cancer-specific molecular target for ATC therapeutics." (PMID 30760700, 2019). "NF-κB, which is activated by TNFα, is involved in the initiation and progression of cancer." (PMID 31591350, 2019). "Furthermore, it was reported that exosomes derived from non-cancer cells can carry endogenous TNF-α, and maintain the CD4+ T cell proliferation index in long-term culture." (PMID 31137684, 2019). "However, we demonstrated for the first time a detectable TNF-α protein in MP derived from cancer cell lines." (PMID 31137684, 2019). "Thus, the specific roles of DCGs in CRC seemto be triggering the metastasis in contrast to their common roles as mediators in TNF, epithelial cell signaling, metabolism, and transportations that was shared with different cancer types." (PMID 29843204, 2019). "Furthermore, IL-1ß, IL-6 and TNF-α are present in the microenvironment of cancer, contributing to metastasis and drug resistance." (PMID 30923340, 2019).